OMD (osteomodulin)
Description:
May be implicated in biomineralization processes. Has a function in binding of osteoblasts via the alpha(V)beta(3)-integrin.
Synonyms: OSAD; SLRR2C; osteoadherin
Tractability: Antibody: its Gene Ontology location is reachable by antibodies, with high confidence; UniProt places it where antibodies can reach, with medium confidence; UniProt predicts a signal peptide or a membrane-spanning region.
Gene: Protein-coding gene on chromosome 9 (92,412,380 to 92,424,471, reverse strand). Ensembl gene ENSG00000127083.
Subcellular location: Secreted, extracellular space, extracellular matrix
Subcellular location (Human Protein Atlas): Endoplasmic reticulum; Nucleoli fibrillar center; Predicted to be secreted
Pathways (Reactome):
Disease: Defective B4GALT1 causes B4GALT1-CDG (CDG-2d); Defective CHST6 causes MCDC1; Defective ST3GAL3 causes MCT12 and EIEE15
Metabolism: Keratan sulfate biosynthesis; Keratan sulfate degradation
Gene Ontology:
Cellular component: extracellular exosome; extracellular region; gel phase of interstitial matrix; Golgi lumen; lysosomal lumen; extracellular matrix
Genetic constraint (gnomAD): Loss-of-function variants: 14 observed, 28.92 expected, observed/expected ratio (o/e) 0.48, 90% interval 0.32 to 0.76. The upper end of that interval is the gene's LOEUF score, 0.76, which puts it in group 3 of 6, group 1 being the genes least tolerant of losing a copy. Missense variants: 423 observed, 488.9 expected, observed/expected ratio (o/e) 0.87, 90% interval 0.8 to 0.94. Synonymous variants: 143 observed, 167.74 expected, observed/expected ratio (o/e) 0.85, 90% interval 0.74 to 0.98.
Homologues: Orthologues: chimpanzee OMD (99% identical), macaque OMD (96% identical), pig OMD (83% identical), rabbit OMD (82% identical), dog OMD (80% identical), guinea pig OMD (79% identical), mouse Omd (79% identical), rat Omd (79% identical), tropical clawed frog omd (52% identical), zebrafish omd (46% identical). Paralogues in human: PRELP (33% identical), KERA (33% identical), LUM (32% identical), FMOD (30% identical), ECM2 (24% identical), LINGO3 (17% identical), LINGO4 (17% identical), OMG (17% identical), EPYC (15% identical), OGN (15% identical).
Diseases named in the same sentence as OMD in open-access papers:
OMD is named in the same sentence as 25 diseases in open-access papers, as found by Europe PMC text mining. Sharing a sentence is not in itself a finding about the gene and the disease. The quoted sentences say what the papers report.
bladder cancer (3 papers, 2020 to 2023). "We showed that in association with a change of EMT states, OMD or PRELP suppression in mice resulted in an initiation of bladder cancer, while the activation of OMD or PRELP inhibited bladder cancer progression in vitro and in vivo." (PMID 33202923, 2020). "Rather, with the present study, we propose OMD as a novel 9q-residing tumor-suppressor gene involved in cancer bladder initiation." (PMID 33202923, 2020). "Furthermore, the ontological analysis of the expression profiling of an OMD knockout mouse bladder demonstrated very high similarity with those obtained from human bladder cancers." (PMID 33202923, 2020). "Furthermore, the overexpression of OMD in bladder cancer cells strongly inhibited the anchorage-independent growth and tumorigenicity in mouse xenograft studies." (PMID 33202923, 2020). "We previously demonstrated the cell-cell junction dysfunction in response to the OMD and PRELP expression levels in bladder cancer cells using electron microscope analysis along with immunofluorescence analysis." (PMID 37936982, 2023). "We previously demonstrated that OMD and PRELP are both expressed in umbrella bladder epithelial cells and involved in bladder cancer initiation in a partially redundant manner." (PMID 37936982, 2023). "More recently, PRELP and osteomodulin, a most highly conserved SLRP member with PRELP, have been also found that they regulate bladder cancer initiation in a functionally partially redundant manner." (PMID 33428936, 2021). "We propose that OMD and PRELP-mediated regulation of EMT is important for the initiation of human bladder cancer." (PMID 33202923, 2020). "We found that OMD and PRELP were specifically expressed in umbrella cells in bladder epithelia, and their expression levels were dramatically downregulated in all bladder cancers from very early stages and various epithelial cancers." (PMID 33202923, 2020). "OMD and PRELP were also downregulated in bladder cancer cell lines compared to normal bladder tissue." (PMID 33202923, 2020). "The downregulation of OMD and PRELP expression was observed in all of the cancers we analyzed, including bladder cancer." (PMID 33202923, 2020). "Our results indicated that although OMD and PRELP share considerable amount of signal pathways, there are some differences in the observed phenotypes: branching, proliferation, bladder cancer progression, and protein expression." (PMID 33202923, 2020). "To investigate the roles of OMD and PRELP at the molecular level, we constructed stable cell lines that overexpressed OMD, OMD-myc, PRELP, and PRELP-myc using the EJ28 bladder cancer cell line, as their endogenous expression is strongly suppressed." (PMID 33202923, 2020). "Here, we found that two secreted proteins of osteomodulin (OMD) and proline/arginine-rich end leucine repeat protein (PRELP) were selectively expressed in bladder umbrella epithelial cells, and they were suppressed in bladder cancer." (PMID 33202923, 2020). "Both OMD and PRELP were downregulated, especially in bladder cancer." (PMID 33202923, 2020). "OMD and/or PRELP may have potential for the treatment of bladder cancer." (PMID 33202923, 2020). "OMD and PRELP may be potential therapeutic targets in bladder cancer." (PMID 33202923, 2020).
osteosarcoma (3 papers, 2021 to 2024). A usually aggressive malignant bone-forming mesenchymal neoplasm, predominantly affecting adolescents and young adults. "In the case of module 3 genes associated with osteosarcoma, eight are found in COSMIC (LUM, COL6A3, TNC, CALU, COL16A1, OMD, ITGB5, and DPSYL3), and two (CDH11 and OMD) are oncogenes found in OncoKB." (PMID 34570764, 2021). "Additionally, five key genes, including CD4, RUNX2, OMD, COL9A3, and JUN, were found to be associated with osteosarcoma progression." (PMID 39324133, 2024). "The expression of CD4, OMD, and JUN was decreased in Osteosarcoma cells compared with osteoblasts, whereas RUNX2 and COL9A3 expression was increased." (PMID 36686663, 2022). "Vincristine, dexamethasone, and vinblastine may form a promising drug–target pair with RUNX2, OMD, and CD4 for Osteosarcoma treatment." (PMID 36686663, 2022).
keloid (2 papers, 2022 to 2024). An irregularly shaped, elevated mark on the skin caused by deposits of excessive amounts of collagen during wound healing. "Osteomodulin (OMD), a protein highly expressed in keloid tissues, has been shown to activate p38 MAPK, potentially enhancing the tumor-like characteristics of KFs." (PMID 39201463, 2024). "The fact that some proteoglycans related to skin mechanical forces (e.g., ASPN, VCAN, and OMD) were also overexpressed in keloids proved the interaction between skin mechanical disorder and keloid formation again." (PMID 35435317, 2022).
osteoporosis (2 papers, 2019 to 2026). A condition of reduced bone mass, with decreased cortical thickness and a decrease in the number and size of the trabeculae of cancellous bone (but normal chemical composition), resulting in increased fracture incidence. "Here we identify osteomodulin (OMD), a matrix-associated osteoblast-derived protein that is reduced in the bone tissue and serum of postmenopausal patients with osteoporosis." (PMID 41813908, 2026).
atherosclerosis (1 paper, 2022). A disease characterized by the build-up of fatty material and calcium deposition in the arterial wall resulting in partial or complete occlusion of the arterial lumen. "The data from these experimental models confirm that OMD protein is associated with developing medial and intimal calcification, which are processes typical for late‐stage human CKD and atherosclerosis, respectively." (PMID 35184400, 2022).
basal cell carcinoma (1 paper, 2022). A carcinoma involving the basal cells. "Interestingly, the terms “basal cell carcinoma” and “TGF-β signaling pathway” were enriched in the KEGG pathways of NPPA, OMD, and PRELP, and acted as the positive pathways." (PMID 36544902, 2022).
cognitive decline (1 paper, 2019). "In particular, we have identified four plasma proteins—BSP, OMD, ACY1, and GHR—with consistent alterations in PD, one of which (GHR) also predicted subsequent cognitive decline in multiple cohorts, across multiple cognitive testing instruments." (PMID 31603904, 2019).
diabetes (1 paper, 2022). "Recent studies in patients reported that plasma levels of osteomodulin (OMD), a proteoglycan involved in bone mineralisation, associate with diabetes and CVD." (PMID 35184400, 2022).
mild cognitive impairment (1 paper, 2025). "For example, a Pennsylvania cohort identified four serum proteins—bone sialoprotein (BSP), osteomodulin (OMD), aminoacylase-1 (ACY1), and growth hormone receptor (GHR)—as PD biomarkers, yet these were not specific to PD when compared to ALS or mild cognitive impairment." (PMID 40699858, 2025).
myeloma (1 paper, 2018). "The recombinant OMD (positive control) was made in a mouse myeloma cell line and runs between 60-66kDa on reducing gels." (PMID 29547667, 2018).
osteoarthritis (1 paper, 2023). A noninflammatory degenerative joint disease occurring chiefly in older persons, characterized by degeneration of the articular cartilage, hypertrophy of bone at the margins and changes in the synovial membrane. "Abnormal subchondral bone remodeling leading to sclerosis is a main feature of osteoarthritis (OA), and osteomodulin (OMD), a proteoglycan involved in extracellular matrix mineralization, is associated with the sclerotic phenotype." (PMID 37730805, 2023).
pulpitis (1 paper, 2025). Inflammation of the dental pulp. "These indicated decreased OMD expression in inflamed dental pulp tissues, suggesting the involvement of OMD in pulpitis progression." (PMID 40414936, 2025). "Intriguingly, the OMD expression decreased in the inflammatory infiltration area of pulpitis specimens." (PMID 40414936, 2025).
tumor (6 papers, 2020 to 2025). "Transcripts for the five genes encoding class II SLRPs (FMOD, LUM, PRELP, KERA and OMD) were quantified in both healthy and tumor tissue, with no significant expression differences between tissue type." (PMID 34440771, 2021). "Among the various subtypes of fibroblasts/myofibroblasts, OMD+ fibroblasts were specifically present in LNM PDAC and were found to create a tumor-permissive microenvironment by recruiting CCL2+ macrophages." (PMID 40092486, 2025). "OMD (osteomodulin) is involved in osteoblast differentiation and OGN (osteoglycin) regulates bone and glucose homeostasis and has been indicated as a tumor suppressor." (PMID 36980828, 2023). "Our result indicates that OMD and PRELP function as tumor-suppressing proteins through inhibiting EMT." (PMID 33202923, 2020). "Given that MMP1 and S100A2 have been identified as important factors in the onset and development of PDAC, further research should investigate the role of MMP1/S100A2 in fostering a tumor-supportive microenvironment, particularly concerning CCL2+ macrophages and OMD+ fibroblasts." (PMID 40092486, 2025).
cancer (4 papers, 2016 to 2024). A tumor composed of atypical neoplastic, often pleomorphic cells that invade other tissues. "Post-treatment cold tumors also acquired more cancer-specific mutations (i.e., BRCA2, TPR, OMD, RANBP2, EP300)." (PMID 38714665, 2024). "In order to examine the in vivo effects of OMD overexpression in cancer development, we performed mouse xenograft experiments using stably transformed EJ28 cells." (PMID 33202923, 2020). "Using the Functional Analysis mode, “molecular mechanism of cancer” was identified as one of the most significantly affected biological functions and/or diseases in all four conditions of OMD overexpression, OMD depletion, PRELP overexpression, and PRELP depletion." (PMID 33202923, 2020). "This potentially means that it is possible to classify a patient’s clinical state based solely on their OMD and PRELP expression status from early-stage cancers." (PMID 33202923, 2020). "The expression of both OMD and PRELP in tumors was drastically lower compared to normal tissues and declined progressively with cancer stage." (PMID 33202923, 2020). "Our data indicate that OMD and PRELP are endogenous inhibitors of cancer initiation and progression by controlling EMT." (PMID 33202923, 2020). "To further assess the role of OMD and PRELP in cancer, we overexpressed or underexpressed the two proteins in cultured cells and performed gene expression analysis using microarrays (Affimetrix GeneChip® System)." (PMID 33202923, 2020). "This study demonstrates that the functions of OMD and PRELP are partially redundant in the regulation of both cell–cell integrity and cancer initiation/progression, and they are potentially important, especially for bladder cell therapeutics." (PMID 33202923, 2020). "The 95 % confidence intervals of the hazard ratios of P4HA3, SRPX2, DCN, OMD, and TCF4 all excluded 1 in multivariate analysis in both cancer sets." (PMID 27809802, 2016). "We found seven upregulated genes (MCM10, RAD51-associated protein 1 (RAD51AP1), KIF2C, Y_RNA, FAM64A, CDC6, and CDCA8) and six downregulated genes (ADAMTS8, ATP1A2, MYH1, OGN, OMD, and ZBTB16) in at least two phenotypes containing either ALT high/middle or TEL high/middle regardless the cancer type." (PMID 38763334, 2024). "Thus, double knockout of OMD/PRELP and E-cadherin may reveal the process of malignant cancer initiation." (PMID 33202923, 2020).
heart disease (1 paper, 2020). "Together with another group of four proteins from the SLRP family, namely fibromodulin (FMOD), osteomodulin (OMD), osteoglycin (OGN) and lumican (LUM), the importance of extracellular remodeling processes in heart disease is emphasized." (PMID 32670412, 2020).
OMD also shares sentences with these, for which no sentence is quoted: bacterial infection (1 paper); biliary atresia (1); breast carcinoma (1); chronic kidney disease (1); enamel caries (1); hypertrophic cardiomyopathy (1); ovarian carcinoma (1); psoriasis (1); type 2 diabetes (1); urothelial carcinoma (1).